VDR (vitamin D receptor)
Diseases named in the same sentence as VDR in open-access papers (continued):
Sharing a sentence is not in itself a finding about the gene and the disease.
uveal melanoma (4 papers, 2019 to 2025). A melanoma derived from melanocytes of the uveal tract. "In light of the positive correlation between uveal tumor pigmentation and metastatic risk, the pattern of VDR expression in uveal melanoma matches closely with that in cutaneous melanoma, implicating similar utility in diagnosis." (PMID 32429485, 2020). "Reduced VDR expression in malignant tissues was also found in other tumors, such as cutaneous and uveal melanomas, urothelial bladder, colon, and lung cancers." (PMID 33227893, 2020). "In the current study a reverse correlation was found between the melanin level and VDR in uveal melanoma." (PMID 31235702, 2019). "In predominantly amelanotic tumors, the levels of VDR were the highest, then VDRn decreased in medium-pigmented (dark brown) uveal melanomas." (PMID 31235702, 2019). "Moreover, cytoplasmic expression of VDR, RORα and RORγ (VDRc, RORαc and RORγc) was observed in the cells of uveal melanoma." (PMID 31235702, 2019). "Our study indicated that the uveal melanoma melanin level inversely correlated with VDR expression." (PMID 31235702, 2019). "Therefore, we propose that higher levels of VDR in uveal melanoma might be connected with a better prognosis in this disease." (PMID 31235702, 2019). "The levels of VDR, CYP24A1, CYP27B1 and RORs were always the lowest in the cells of uveal melanoma and higher in normal uveal melanocytes and other normal uveal cells." (PMID 31235702, 2019). "To fill the gap in our knowledge on vitamin D activity in uveal melanoma, we decided to evaluate the expression pattern of the VDR, CYP27B1 and CYP24A1 hydroxylases and RORα and RORγ in the cells of uveal melanoma, in normal melanocytes and in other normal uveal cells in humans." (PMID 31235702, 2019). "In conclusion, we provide an evidence for the presence of the VDR, CYB27B1, CYP24A1, RORα and RORγ in uveal cells, which changes in uveal melanomas and suggest that these proteins are involved in clinical presentation and represent targets for novel therapeutic approaches." (PMID 31235702, 2019). "This is significant because until now there has been no paper published, that would describe presence of VDR, hydroxylases CYP27B1 and CYP24A1, and RORα and RORγ in the human uveal tract and uveal melanomas." (PMID 31235702, 2019).
Vitamin D (4 papers, 2015 to 2025). "Vitamin D/VDR deficiency is a health concern in metabolic diseases." (PMID 30828578, 2018).
acne (3 papers, 2021 to 2025). An inflammatory process of the sebaceous glands which is characterized by comedones, nodules, papules and/or pustules on the skin. "In patients with acne vulgaris, genetic variations in the VDR gene are significantly associated with reduced serum 25-hydroxyvitamin D3 (25(OH)D3) levels." (PMID 40681996, 2025). "The VDR-FokI polymorphism CC genotype had a significant protective role in the odds of acne (OR = 0.11, 95% CI: [0.02, 0.70], p = 0.015, p-corrected = 0.040) and seborrhea (OR = 0.15, 95% CI: [0.03, 0.75], p = 0.019, p-corrected = 0.039)." (PMID 39336541, 2024). "One recent study was focused on the associations between VDR-ApaI and VDR-TaqI polymorphisms and acne vulgaris." (PMID 39336541, 2024). "Therefore, the results showed the interaction between PCOS and the VDR-FokI polymorphism regarding the odds of acne and seborrhea." (PMID 39336541, 2024). "These polymorphisms may impair VDR-mediated transcriptional activity or ligand binding, exacerbating vitamin D deficiency and its downstream effects on sebocyte regulation, inflammation, and microbial defense in acne pathogenesis." (PMID 40681996, 2025). "In addition, the following variants were significantly associated with acne risk: ADH7 (alcohol dehydrogenase 7) rs1154469, SRD5A2 (steroid 5 alpha-reductase 2) TA repeat VNTR and VDR (vitamin D receptor) rs731236 and rs7975232." (PMID 33849530, 2021). "Thus, variants in VDR, IL6 and IL8 may affect sebaceous gland function and contribute to acne development or exacerbation." (PMID 33849530, 2021). "We found the T allele of the VDR-Fokl gene polymorphism in 52.5% and 16.7% and the C allele in 47.5% and 8.3% of PCOS cases with acne and PCOS cases without acne, respectively." (PMID 39336541, 2024). "The study demonstrated that the FokI CC genotype may have a protective role against both acne and seborrhea in women with PCOS, and also, the VDR-TaqI dominant genotype may have a protective role against oxidative stress in PCOS patients." (PMID 39336541, 2024).
acute lymphoblastic leukemia (3 papers, 2018 to 2024). Leukemia with an acute onset, characterized by the presence of lymphoblasts in the bone marrow and the peripheral blood. "Vitamin D analogs (VDAs) may directly inhibit the growth of normal and malignant (derived from acute lymphoblastic leukemia (ALL)) B cells, as both types of cells express vitamin D receptor (VDR)." (PMID 35456315, 2022).
adrenocortical tumors (3 papers, 2015 to 2022). "Studies in literature that investigate the correlation between vitamin D and tumors of the adrenal cortex, although few, seem to have a single direction, underlining the important role of VDR in carcinogenesis." (PMID 36313775, 2022). "enrolling pediatric patients with pediatric adrenocortical tumors (pACT) and studied VDR expression levels and methylation status in pACTs and their clinical and prognostic significance." (PMID 36313775, 2022). "It considered clinical and pathological features, mRNA (qPCR) and protein (immunohistochemistry) expression of VDR and methylation at the VDR level of adrenocortical tumor samples from 108 pediatric patients." (PMID 36313775, 2022). "Reduced levels of vitamin D and under-expression of VDR seem to have a role in tumors of the adrenal cortex." (PMID 36313775, 2022). "We analyzed methylation of CpG sites in the VDR gene promoter in normal adrenals and adrenocortical tumor samples." (PMID 26843863, 2015). "Similarly, pediatric adrenocortical tumors with high VDR promoter methylation had lower VDR mRNA levels and correlated with advanced disease and reduced survival in these patients." (PMID 36246903, 2022). "There is also evidence that a number of short noncoding RNAs may repress VDR posttranscriptional regulation in cancer, and their specific role as VDR regulators in adrenocortical tumors is possible." (PMID 26843863, 2015).
allergic rhinitis (3 papers, 2015 to 2025). Inflammation of the nasal mucous membranes caused by an IgE-mediated response to external allergens. "Based on these previous findings, we hypothesize that VDR and CYP2R1 are candidate genes for susceptibility to allergic rhinitis." (PMID 26177022, 2015).
Alopecia universalis (3 papers, 2022 to 2025). Alopecia universalis is the most severe form of alopecia areata, an inflammatory disease of the hair follicle, which is characterized by a complete loss of hair of the scalp and all the hair-bearing areas of the body. "The crosstalk between VDR expression and AA is tightly innervated with each other.The mutation of VDR expression has been observed in patients with AA and alopecia universalis (AU)." (PMID 40681996, 2025). "The role of the vitamin D receptor (VDR) in the hair cycle was suspected by the observation of alopecia universalis in a rare genetic disorder called type II vitamin D-dependent rickets (VDDR IIA)." (PMID 35276950, 2022).
arteriosclerosis (3 papers, 2014 to 2023). A vascular disorder characterized by thickening and hardening of the walls of the arteries. "In addition, severe chronic inflammation in the liver, impaired glucose metabolism, and the promotion of arteriosclerosis have been reported in myeloid-specific VDR knockout mice fed HFD." (PMID 36774476, 2023).
Arthralgia (3 papers, 2019 to 2023). "SNPs in steroid 17-alpha-hydroxylase/17,20 lyase (CYP17A1) and vitamin D3 receptor (VDR) genes were significantly associated with treatment-related arthralgia (p = 0.003 and p = 0.012, respectively)." (PMID 33530456, 2021). "Furthermore, variations in cytochrome P450 (CYP) and vitamin D receptor (VDR) genes have been associated with aromatase inhibitor-related arthralgia." (PMID 31196165, 2019).
B-cell lymphoma (3 papers, 1993 to 2026). "We have evaluated the activity of 1,25(OH)2D3 and its non-calcaemogenic analogue MC903 in the SU-DHL4 and SU-DUL5 B cell lines which carry the 14;18 translocation characteristic of follicular NHL, and also the expression of the VDR in a range of B cell NHLs." (PMID 8398690, 1993).
bladder tumors (3 papers, 2015 to 2020). "This suggests that the association between the expression of the VDR and bladder tumor biology is complex." (PMID 26501255, 2015). "VDR was found positive immunohistochemically in 86–100% of bladder tumors." (PMID 26770009, 2015). "Thus, VDR signals appear to play a protective role in bladder tumor outgrowth." (PMID 26770009, 2015).
Calcium nephrolithiasis (3 papers, 2014 to 2021). The presence of calcium-containing calculi (stones) in the kidneys. "Genetic polymorphisms of CLDN14, CASR, OPN, ORAI1, and VDR were reported to be involved in calcium nephrolithiasis in humans." (PMID 24800221, 2014).
carcinoma in situ (3 papers, 2010 to 2023). "A specific correlation was also found between VDR, enzymes involved in Vitamin D metabolism and cancer cell differentiation: high levels are observed in carcinoma in situ, whereas low levels are found in invasive seminoma." (PMID 37242266, 2023). "We successfully detected VDR expression in both normal human urothelium and carcinoma in situ (CIS) so as to suggest a potential vitamin D action in the human bladder." (PMID 24353168, 2013). "The VDR is also highly expressed in benign lesions (93.5%) with a reduction in the percentage of positive cases in carcinomas in situ (47.3%) and in invasive carcinomas (56.2%)." (PMID 20831823, 2010). "We have used a cohort comprising normal breast, benign mammary lesions, carcinomas in situ and invasive carcinomas and assessed the expression of the VDR, CYP27B1 and CYP24A1 by immunohistochemistry." (PMID 20831823, 2010). "As far as we know, our study is the first to investigate the immunohistochemical expression of the VDR in a range of benign lesions and carcinomas in situ of the mammary gland." (PMID 20831823, 2010). "The series of 189 tumours with both components (carcinomas in situ and the corresponding invasive tumour) allowed the evaluation of the expression of the VDR, CYP27B1 and CYP24A1 simultaneously in the two types of tumours." (PMID 20831823, 2010). "The percentage of positive cases for the VDR is higher in benign lesions than in invasive tumours (93.5% and 56.2%, respectively), while the carcinomas in situ display the lowest value of all (47.3%)." (PMID 20831823, 2010). "In fact, the VDR is expressed in most ER-positive cases (54.7% in in situ carcinomas and 65.5% in invasive tumours)." (PMID 20831823, 2010). "The results obtained show that the three proteins (VDR, CYP27B1 and CYP24A1) display a statistically significant correlation of expression between the two sections (carcinomas in situ and the matching invasive tumour)." (PMID 20831823, 2010).
chronic pancreatitis (3 papers, 2014 to 2023). A chronic inflammatory process causing damage and fibrosis of the pancreatic parenchyma. "In chronic pancreatitis patients the significant correlation of CYP24A1 and VDR suggests that high CYP24A1 expression in the islets is a physiological up-regulation of CYP24A1." (PMID 25090635, 2014). "Finally, this study did not compare acute and chronic pancreatitis, which might affect VDR, CYP24A1, and CYP27B1 expression levels." (PMID 37808100, 2023).
colon adenocarcinoma (3 papers, 2022 to 2024). "Comparing the different entities, the highest expression of VDR was found in rectal and colon adenocarcinoma and kidney cancer, directly followed by HNC, supporting our conclusions obtained from the analyses of our cohort." (PMID 36902107, 2023). "Comparing different malignancies, high expression of the VDR was found not only in colon adenocarcinomas but also in HNSCC, supporting a potential pathobiological relevance of the VDR for this tumor entity." (PMID 36291915, 2022).
cyst (3 papers, 2021 to 2025). A sac-like closed membranous structure that may be empty or contain fluid or amorphous material. "The VDR-AdV-infected rats showed remarkable hair growth, reduced hair loss, low cyst formation, and significant expression of VDR." (PMID 37898650, 2023). "Glutamatergic synapse,-hydroxyeicosatetraenoic acids, lipophagy, and retinoid X receptor coupled with vitamin D receptor were the most significantly enriched pathways in healthy control, abscess, cyst, and granuloma, respectively." (PMID 34539639, 2021). "New cyst formation was suppressed in VDR-AdV-injected rats compared to that in both non-injected (control) and control-AdV-injected rats." (PMID 37898650, 2023).
emphysema (3 papers, 2013 to 2023). "In VDR knockout mice, an increase in inflammatory cell infiltration, upregulation of metalloproteinases, and phosphoacetylation of NF-κB were observed in the lung, which was associated with emphysema and a decline in lung function along with the formation of lymphoid aggregates." (PMID 37299440, 2023). "Interestingly, studies suggested that an alteration in VDR/vitamin D3 axis in mouse alveolar macrophages may lead to pulmonary emphysema." (PMID 33133014, 2020).
esophageal cancer (3 papers, 2017 to 2019). A primary or metastatic malignant neoplasm involving the esophagus. "The TaqI polymorphism of VDR is associated with the risk of tobacco-related respiratory system and esophagus cancers." (PMID 31690771, 2019). "Esophageal cancer (squamous cell), showed significant enrichment in more than one VDR dataset (p = 0.0001), and it was also amongst the significant traits within the ligand-stimulated ChIP-seq dataset in the CEPH cell line." (PMID 28166722, 2017). "However, we could not identify reports investigating chemosensitivity with regard to TCF, Src, caspase-1, VDR, BLIMP-1, PDGFR, and IL-1 in esophageal cancer." (PMID 29136005, 2017).
esophageal squamous cell carcinoma (3 papers, 2017 to 2024). Esophageal squamous cell carcinoma (ESCC) is a type of esophageal carcinoma (EC) that can affect any part of the esophagus, but is usually located in the upper or middle third. "Bile acid receptors, including FXR, the Takeda G-protein-couples receptor 5 (TGR5) and VDR, have recently been identified in EAC and esophageal squamous cell carcinoma (ESCC)." (PMID 28212604, 2017).
experimental autoimmune encephalomyelitis (3 papers, 2011 to 2020). An autoimmune demyelinating disease of the central nervous system that is produced experimentally in animals by the injection of homogenized brain or spinal cord in Freund's adjuvant. "Mice with VDR specific KO in T cells have increased incidence of experimental autoimmune encephalomyelitis and VDR expression in T cells was shown to be essential for the effectiveness of 1,25(OH)2D3 for the suppression of disease." (PMID 24502291, 2014). "In mouse models of autoimmune disease, 1,25(OH)2D3 suppresses Th1 and Th17-mediated inflammation, and T cell VDR expression is required for 1,25(OH)2D3-mediated inhibition of experimental autoimmune encephalomyelitis (EAE)." (PMID 21738762, 2011). "Also, T cell VDR expression is required for 1,25(OH)2D3-mediated inhibition of experimental autoimmune encephalomyelitis in mice." (PMID 21738762, 2011).
fetal growth restriction (3 papers, 2017 to 2023). A fetus that does not grow beyond the 10th percentile of conventionally accepted weight for gestational age. "It will also be important to further put these findings into context, e.g., given the roles of VDR and Snail in mechanisms of placental differentiation and pregnancies with fetal growth restriction." (PMID 36146811, 2022).
follicular adenoma (3 papers, 2017 to 2025). "Moreover, VDR was observed among genes overexpressed in the follicular variant of PTC comparing to follicular adenoma." (PMID 36362448, 2022). "When DTC was compared to follicular adenoma, significantly higher VDR and lower CYP24A1 expression was observed." (PMID 28895880, 2017). "Later, these findings were reproduced by other groups which reported that VDR, CYP27B1, and CYP24A1 expressions were increased in follicular adenoma and DTC, such as PTC and follicular thyroid cancer (FTC), when compared to normal thyroid tissue." (PMID 28895880, 2017).
gastric adenocarcinoma (3 papers, 2018 to 2024). "All alteration types of VDR were found in stomach adenocarcinoma and amplification of VDR was observed in all uterine carcinosarcoma and sarcoma." (PMID 38639057, 2024). "The current study aimed to evaluate VDR expression, cell proliferation, and apoptosis in gastric adenocarcinoma samples using digital quantitative immunohistochemistry (IHC) statin analyses." (PMID 34881266, 2021). "Because the major type of gastric adenocarcinoma was poorly differentiated in this study, similar VDR expression in the mucosa adjacent to the tumor may be found in patients with poorly differentiated gastric adenocarcinoma." (PMID 34881266, 2021). "Further, CD24 mediates gastric adenocarcinoma cell survival and invasion by activating STAT3 signaling and regulating extracellular matrix protein and VDR expression." (PMID 29772698, 2018).
glaucoma (3 papers, 2009 to 2021). Increased pressure in the eyeball due to obstruction of the outflow of aqueous humor. "Our analysis of glaucomatous astrocytes indicated that the synergistic activation of the major hubs SP-1, VDR, NF-κB and AP-1 in response to oxidative stress and mild ischemia associated with glaucoma, orchestrates genome-wide changes in the transcriptional profile and chronic activation of ONHAs." (PMID 19426536, 2009). "Re-analysis of GSE26299, showed that vitamin D receptor (VDR) expression is increased in ONH of DBA/2J mice (severe glaucoma) compared to control Gpnmb knock-in transgenic mice (D2-Gpnmb+ control)." (PMID 34530842, 2021).
gout (3 papers, 2021 to 2025). A condition characterized by painful swelling of the joints, which is caused by deposition of urate crystals. "The combined effects of decreased BA synthesis and an altered BA pool decrease the activities of FXR, TGR5, and VDR, which subsequently induce or promote inflammatory responses, thereby exacerbating the progression of gout." (PMID 41255527, 2025). "In gout, diminished levels of secondary BAs lead to decreased VDR activation, which results in attenuated inhibition of NF-κB signaling." (PMID 41255527, 2025).
hepatitis C (3 papers, 2012 to 2023). "Recently the effect of the Vitamin D receptor signaling on the fibrogenesis was explored in a Hepatitis C infected population." (PMID 23342360, 2012). "The SNPs BsmI and TaqI could potentially contribute to a worsening of the clinical course of hepatitis C by downregulating VDR expression and thus its immunomodulatory activity." (PMID 37511164, 2023).
Hodgkins lymphoma (3 papers, 2012 to 2022). A heterogeneous group of malignant lymphoid neoplasms of B-cell origin characterized histologically by the presence of Hodgkin and Reed-Sternberg (HRS) cells in the vast majority of cases. "Expression of VDR in Hodgkin lymphoma has been reported recently." (PMID 32513132, 2020). "Mixed cellularity cases showed predilection for focal VDR and FOXP3 expression (80% cases); whereas nodular sclerosis subtype had focal and diffuse VDR and FOXP3 expression patterns in similar proportion." (PMID 32513132, 2020). "Mixed cellularity cases showed predilection for focal VDR and FOXP3 expression (80% cases); whereas nodular sclerosis subtype had focal and diffuse patterns in similar proportion of cases 47.4 and 36.8% respectively." (PMID 32513132, 2020). "VDR was expressed regardless of the Hodgkin disease (HD) subtype with an overall positivity of 82% cases and FOXP3 was expressed in 78%, also regardless of HD subtype." (PMID 32513132, 2020).